C19orf38 (chromosome 19 open reading frame 38)
Synonyms: HIDE1
Tractability: Antibody: UniProt predicts a signal peptide or a membrane-spanning region.
Gene: Protein-coding gene on chromosome 19 (10,836,567 to 10,869,791, forward strand). Ensembl gene ENSG00000214212.
Subcellular location: Membrane
Subcellular location (Human Protein Atlas): Cytosol; Golgi apparatus; Plasma membrane
Gene Ontology:
Molecular function: protein binding
Cellular component: membrane
Genetic constraint (gnomAD): Loss-of-function variants: 14 observed, 28.57 expected, observed/expected ratio (o/e) 0.49, 90% interval 0.32 to 0.77. The upper end of that interval is the gene's LOEUF score, 0.77, which puts it in group 3 of 6, group 1 being the genes least tolerant of losing a copy. Missense variants: 261 observed, 308.97 expected, observed/expected ratio (o/e) 0.84, 90% interval 0.76 to 0.94. Synonymous variants: 132 observed, 134.33 expected, observed/expected ratio (o/e) 0.98, 90% interval 0.85 to 1.13.
Homologues: Orthologues: chimpanzee C19H19orf38 (97% identical), macaque C19H19orf38 (90% identical), pig C19orf38 (76% identical), dog C19orf38 (74% identical), rabbit C19orf38 (74% identical), guinea pig C19orf38 (72% identical), mouse AB124611 (69% identical), rat C8h19orf38 (67% identical).
Diseases named in the same sentence as C19orf38 in open-access papers:
C19orf38 is named in the same sentence as 1 disease in open-access papers, as found by Europe PMC text mining. Sharing a sentence is not in itself a finding about the gene and the disease.
C19orf38 shares sentences with these, for which no sentence is quoted: leiomyoma (1 paper).